CTSD (cathepsin D)
Diseases named in the same sentence as CTSD in open-access papers (continued):
Sharing a sentence is not in itself a finding about the gene and the disease.
cancer (continued). "The inhibition of CTSD activity is one of the targets for cancer treatment by controlling the expression of CSTA." (PMID 35976950, 2022). "This proteomics approach revealed that cathepsin D (CTSD) is the main off-target of DR in human cancer cells." (PMID 35682614, 2022). "Cathepsin D (Cat D) is well known for its roles in metastasis, angiogenesis, proliferation, and carcinogenesis in cancer." (PMID 35121737, 2022). "The abundance of cathepsin D outside the lysosomes in malignant tumors makes it a convenient marker and a target for cancer treatment." (PMID 34198733, 2021). "We further probed the changes in cancer dormancy-relevant genes CTSD, THBS1 across pseudo-time, and tissue of origin using Monocle2." (PMID 34579762, 2021). "Some research suggests the roles of cathepsin D in cancer cells in maintaining lysosomal integrity, redox balance and nuclear factor erythroid 2-related factor 2 activity, thus, promoting tumorigenesis." (PMID 34198733, 2021). "We identified CREB as one of the molecular players that mediate the development of cancer cell-intrinsic resistance to the CTSD knockout." (PMID 33046706, 2020). "Herein, cathepsin D expression was correlated with reduced cancer-free survival and as an independent factor for poor prognosis." (PMID 33266503, 2020). "We concluded that the immersion of cathepsin D with an acidic pH in the hypoxic regions of solid tumors conduces a proteolytic cascade that accelerates cancer cell invasion and metastasis." (PMID 32846884, 2020). "Pro-cathepsin D, the inactive precursor of lysosomal aspartyl proteinase cathepsin D, is overexpressed and secreted by several types of cancer cells such as breast, liver, and lung cancer and cancerous cell lines." (PMID 32867726, 2020). "As a lysosomal aspartyl protease, cathepsin D is related to the metastasis of estrogen-dependent cancer cells." (PMID 29316692, 2018). "Based on the ability to induce the EMT process, E2 and CYP were found to promote the migration and invasion of Ishikawa cancer cells and to increase the protein expression of metastasis-related genes, such as Cathepsin D and MMP-9, in the ER-dependent pathway." (PMID 29316692, 2018). "It has been reported that cathepsin D activates cathepsin B and then activates urokinase-type plasminogen activator to increase the number of malignant cancer cells." (PMID 28402938, 2017). "It is noteworthy that most of the current literature on cathepsin D and cancer consider the enzymatically inactive precurs, procathepsin D, to be the relevant molecule." (PMID 29375176, 2017). "CTSB and CTSD were identified to be associated with various cancer types, and we previously showed that CTSB and CTSD play important roles in NPC development and metastasis." (PMID 26995190, 2016). "Elevation of CTSB and CTSD levels in biological fluid has been observed in patients with inflammatory diseases and many cancers." (PMID 26995190, 2016). "We then focus on the opposing functions of cathepsin D in apoptosis, particularly relevant in cancer research." (PMID 28357298, 2015). "Among cathepsins, cathepsin D (CatD) has attracted increased attention in recent years due to its importance in the mediation of lysosomal cell death pathways and in cancer." (PMID 28357298, 2015). "For example, an acidic extracellular pH has been shown to activate gelatinase activity and cathepsin D production, which helps increase the invasiveness of cancer cells." (PMID 25298213, 2014). "Cathepsin D, which features proteolytic activity, serves as a prerequisite for cancer invasion, and its expression is significant in predicting HCC prognosis." (PMID 24614035, 2014). "CTSD, a lysosomal aspartate proteolytic enzyme, also plays a role in invasion and metastasis of cancer." (PMID 24717913, 2014). "Cathepsin D has been postulated to be secreted from cancer cells and been shown to serve as an autocrine growth factor in several cancer studies conferring proinvasive and prometastatic properties." (PMID 22919486, 2012).
cancer (continued). "Expression of cathepsin D in the MTB was inversely correlated with 5-year cancer-specific survival in univariate analysis using Kaplan-Meier statistics and log-rank test." (PMID 22919486, 2012). "Accumulating studies have provided evidence that protein levels of CTSD are an independent biomarker for better prognostic outcome in various cancers." (PMID 22291950, 2012). "Although Res has been shown capable to induce cancer cell death through lysosomal cathepsin D and L release, in our experiments the inhibition of lysosomal cathepsins by pharmaceutical protease inhibitors did not delay the death process." (PMID 22957077, 2012). "Those with strong expression of cathepsin D had a 5-year cancer-specific survival of 42%, compared with 63% for those with moderate expression (P = 0.039) and 81% for those with weak expression (P = 0.0001)." (PMID 22919486, 2012). "5′-O-L-phenylalanyl-L-tyrosylfloxuridine has the capability of being a cathepsin D-targeted prodrug for enzymatic activation and exhibits the respectable growth inhibition of cancer cells." (PMID 22450679, 2012). "In this report, the feasibility of cathepsin D targeting for the activation of amino acid/dipeptide monoester prodrugs of floxuridine and the capability of inhibiting cancer cell growth for those activated prodrugs are described." (PMID 22450679, 2012). "Many studies found that cathepsin D preproprotein/cathepsin D level represents an independent prognostic factor in a variety of cancers and is, therefore, considered to be a potential target for anticancer therapy." (PMID 22110952, 2011). "Increased tissue expression of cathepsin D has been correlated with poorer outcome in a number of other cancers, although inconsistently." (PMID 19789534, 2009). "We detected variations in quantity of cathepsin D, cathepsin B, squamous cell carcinoma antigen, γ synuclein, cytokeratin 19 and other proteins that have been reported to play a role in cancer etiology." (PMID 18416831, 2008). "Another unexpected observation of the present work was the robust induction of cathepsins B, C, D and Z, in the invasive CR2-TAg cancer stroma mimicking the almost exclusively stromal cathepsin D expression pattern in human SCLC and LCNEC." (PMID 17183660, 2006). "TIMP-2 expression by cancer cells was associated with peritumoral lymphovascular invasion, and expression of HSP-27, cathepsin D and uPA by stromal cells." (PMID 16776850, 2006). "Acidic extracellular pH has been shown to activate gelatinase activity and production of cathepsin D, which contribute to an increased cancer cell invasive ability." (PMID 12942121, 2003). "Overexpression of proteases has been reported in many cancers, such as of urokinase plasminogen activator, cathepsin D, and matrix metalloproteinase." (PMID 12087468, 2002). "In addition, serum Cys levels can be lowered irrespective of renal function by cancer treatment, likely due to the release of a Cys cleaving protease, Cathepsin D, from tumor tissue or from the reduction of cancer cells." (PMID 40589793, 2025). "However, in other studies, CTSD acted as a sensitiser, increasing cancer cell death following treatment with chemotherapy drugs." (PMID 40796615, 2025). "The upregulation of cathepsin D and L in myocyte EVs suggests that these proteins could induce apoptosis of carcinoma cells via the intrinsic pathway." (PMID 41300368, 2025). "BCSS of patients with cancers expressing Cathepsin D was analysed according to HER2 status." (PMID 38578521, 2024). "CTSB, CTSL and CTSD were chosen due to their high expression, known function in bulk proteolysis and their reported functional importance such as cell growth and in diseases like cancer and neurodegeneration and neurodegeneration." (PMID 38775843, 2024). "DKK1, CTSB, CTSD, and CAPG are also associated with the metastatic potential of cancer." (PMID 37439806, 2024).
cancer (continued). "However, the role of Cathepsin-D in cell death appears to be the multifaceted, depending on its localization, condition of cells, and context in cancer cells." (PMID 37108361, 2023). "Cathepsin D is an aspartic protease overexpressed in many different cancer types." (PMID 37896224, 2023). "Contrastingly, cathepsin D could also be used as an efficient cancer drug delivery target due to its abundance in the TME." (PMID 37896224, 2023). "Pepstatin-A-functionalized liposomes could be successfully utilized in diagnostics, taking advantage of the significant overexpression of cathepsin D in various types of cancer." (PMID 37896224, 2023). "Moreover, cathepsin D, secreted by cancer cells, acts as a mitogen on both cancer and stromal cells and stimulates their invasive and metastatic properties." (PMID 35205296, 2022). "As pro-cathepsin D promotes cell proliferation, elevated pro-cathepsin might be beneficial to cancer cell growth." (PMID 33445607, 2021). "Although it is primarily located within lysosomes in physiological conditions, CTSD overexpression in cancer cells results in hypersecretion of this protease, which might eventually lead to its increased activity in saliva." (PMID 33578082, 2021). "Compared with non‐PM tissues, we found that among 58 adipokines tested, the 2 adipokines that were most abnormally expressed in PM tissues were adiponectin and cathepsin D. It was consistent with reports that cathepsin D enhances cancer invasion and metastasis." (PMID 33528867, 2021). "Numerous studies found that cathepsin D level may represent an independent prognostic factor in many cancers and is considered a potential target of anticancer therapy." (PMID 34198733, 2021). "Similar to the cytokine profiling results, most of the cancer‐associated proteins, such as ANGPTL4, KLK5, GAL3, VIM, HERs, CAPG, HO, CTSD, and AFP were produced at higher levels on the aged matrix, but were reduced to young matrix levels after LOX siRNA treatment." (PMID 34617419, 2021). "CTSD also has a pivotal role in the regulation of angiogenesis, metastasis, invasion, apoptosis, and cell proliferation; therefore, it is considered a potential therapeutic target for natural products in cancer chemoprevention." (PMID 32244796, 2020). "Among the proteins whose levels were increased by L1 expression in CRC cells, we studied the role of the aspartate protease cathepsin D (CTSD), a lysosomal and secreted protein, because numerous studies reported on its association with the development of cancer in various tumors." (PMID 33228199, 2020). "Cathepsin D is a lysosomal protease which plays a pivotal role in protein catabolism, having an impact on several pathophysiological processes, such as organ development, neurodegeneration, or cancer." (PMID 31960265, 2020). "While the most clinically studied cathepsins in cancer progression have revolved around cathepsin D, progress has indeed broadened towards looking at other cathepsins for their usefulness in such assays, permitting their importance in cancer progression to come into focus." (PMID 33266503, 2020). "Studies have reported increased overexpression and hypersecretion of CTSD in many cancer types." (PMID 32244796, 2020). "The mislocalization of pro-cathepsin D has been observed in several types of cancer cells." (PMID 31332264, 2019). "Previous research demonstrated that GAELs induced an apoptosis-independent form of cancer cell death that may involve altering lysosomal permeability to allow the release of acid proteases such as cathepsin D." (PMID 28499442, 2017). "Furthermore, we showed that overexpression of LAPTM5 in several cancer cells induces lysosomal cell death due to lysosomal destabilization, indicated by leakage of lysosomal cathepsin D into the cytosol as well as impairment of autophagy." (PMID 27058622, 2016).
cancer (continued). "Intense expression of CTSD in high-grade carcinomas might be an indicator of invasive potential and aggressive behavior." (PMID 26995190, 2016). "Finally, we discuss how insights from yeast cathepsin D and its role in regulated cell death can unveil novel functions of mammalian cathepsin D in apoptosis and cancer." (PMID 28357298, 2015). "In particular, cathepsin D is often overexpressed and hypersecreted in cancer cells, implying it may constitute a therapeutic target." (PMID 28357298, 2015). "Generally, CTSD plays a role in apoptosis, innate immune response, and inflammation but also stimulates growth, invasion, migration, angiogenesis, and cellular senescence in cancer cells." (PMID 26056562, 2015). "We hypothesized that inhibiting lysosome exocytosis would reduce cathepsin D release and lead to reduced cancer invasion." (PMID 23029308, 2012). "Among them, Cathepsin B and Cathepsin D may be prognostic markers of cancer." (PMID 39080685, 2024). "Cathepsin D, a soluble lysosomal aspartic protease has many biological functions and is involved in the degradation of proteins, regulation of cell death, and activation of inflammatory cells and plays a crucial role in promoting cancer invasion, metastasis, and angiogenesis." (PMID 37280603, 2023). "Likewise, the expression of cathepsin D is related to cancer cell migratory potential and motility." (PMID 34012396, 2021). "Furthermore, CTSD could act as a key paracrine communicator between cancer and stromal cells, independently of its catalytic activity." (PMID 32244796, 2020). "Thus, MPE, another form of primary cancer progression that can be difficult to diagnose, may be aided by novel biomarker pro-cathepsin D in diagnosis." (PMID 32867726, 2020). "Additionally, we show that storage pathology is co-occurring with alterations in the levels of lysosomal enzymes, such as TPP1 and CTSD, which have been described in various pathological conditions such as neurodegenerative lysosomal storage disorders, inflammation, cancer and aging." (PMID 31888773, 2019). "Thus, the function of increased CTSD expression in cancer cells requires further investigation." (PMID 26056562, 2015). "Based on this as well as on multiple evidence indicating that CTSD and LOXL2 have pro-proliferative functions, inhibition of CTSD and LOXL2 have been suggested as a therapeutic approach for various cancers." (PMID 41185039, 2025). "Increased P2RX4 expression was observed to also promote lysosomal exocytosis, allowing higher concentrations of CTSD to be released into the extracellular matrix, promoting degradation of the ECM and enhancing the invasive properties of cancer cells." (PMID 41009609, 2025). "Notably, cathepsin D can activate the precursor of cathepsin B, which further activates cathepsin D and transports cathepsins B and D between cells through the actin skeleton and microtubules, thereby degrading the extracellular matrix and promoting cancer cell migration and invasion." (PMID 37833712, 2023). "Although not directly demonstrated for HCC, studies using other types of cancer demonstrated a role for both CTSL and CTSD in angiogenesis." (PMID 36289617, 2022). "Subsequently, we will discuss the function of the most studied cathepsins (CTSB, CTSD, CTSL, and cathepsin (CTS)S) in NASH, followed by a description of the mechanisms of cathepsins in HCC by means of the renowned “hallmarks of cancer”." (PMID 36289617, 2022). "Considering that biological phenotypes of cancer, such as cell proliferation and anchorage-independent growth, are mirrored by changes in gene expression, we next investigated whether the selected progestogens could modulate the expression of the known ER-regulated CTSD gene." (PMID 36187129, 2022). "Considering the role of CTSD and CTSL in other cancer types and their overexpression in HCC, these data suggest that these cathepsins also stimulate invasion and metastasis in the context of HCC." (PMID 36289617, 2022).
cancer (continued). "The results showed that APOE, CTSD, LGALS2, and TMEM176B expression in normal tissues was significantly higher than that in cancer tissues (P < 0.01)." (PMID 34873574, 2021). "Proclarix (Proteomedix) combines tPSA and fPSA with cancer-related glycoproteins thrombospondin-1 (THBS1) and cathepsin D (CTSD) as well as age to calculate a patient’s probability of having clinically significant PC on biopsy." (PMID 34948334, 2021). "This immunoassay-based ELISA test is performed on the same blood sample as the sPSA test, measuring the cancer-related glycoproteins thrombospondin-1 (THBS1) and cathepsin D (CTSD)." (PMID 33339117, 2020). "We originally discovered two cancer-related proteins thrombospondin-1 (THBS1) and cathepsin D (CTSD) using a mass-spectrometry-based proteomics approach." (PMID 32421745, 2020). "Other molecules, such as CP, CERLD2, CTSD, HSPA5, HTR3A and TUBB2C, are also frequently up-regulated in cancer." (PMID 28056051, 2017). "Expression of breast cancer 1 (BRCA1), breast cancer 2 (BRCA2), cathepsin D (CTSD), BCL2, and WISP2 were significantly increased." (PMID 27379522, 2016). "The strongest overexpressed proteins in treated Caco-2 exosomes (eg, CD59, CRP, CTSD, HMMR, TRIM22) are involved as potential oncogenes in the pathogenesis of different cancers, including CRC." (PMID 25594007, 2014). "The increased activity of lysosomal protease Cathepsin D, the transcriptional upregulation of autophagy-related MAPLC3B gene in cancer cells and the changes in autophagy-related proteins may have indicated the activation of autophagy." (PMID 36672225, 2023). "Cathepsin B and Cathepsin D release into the cytosol promoted the cleavage and activation of BID, and Dcf1 also decreased the expression of Bcl‐2 to induce the release of proapoptotic factors and enhance the levels of cancer suppressors." (PMID 34799992, 2022). "The genes ITGA3, HSPA8, CTSD, ATG12, CLN3, ATG7, and MAP1LC3C negatively influenced patient survival, whereas WIPI1 may protect the patients from cancer-related death." (PMID 35186475, 2022). "CTSD and proCTSD interact with many important molecules, such as FGF, IL-1, and myosin, to induce their degradation or participate in multiple processes, including apoptosis or cancer development." (PMID 33391533, 2021). "Such destabilization of lysosomes specifically occurs in cancer cells, followed by the release of lysosomal enzymes, including Cathepsin B and Cathepsin D. Cathepsin B mainly contributes to TNF‐α‐induced necrosis, while Cathepsin D evokes apoptosis." (PMID 34523247, 2021). "A recent report suggested that AGR2 may promote cancer cell invasion by increasing the expressions of MUC1 and lysosomal enzymes cathespin B and cathepsin D; thus, AGR2 overexpression plays an important role in invasion, grading, and prognosis of HNSCC." (PMID 25871396, 2015). "5-year cancer-specific survival was not significantly different between those with weak expression of cathepsin D and those with moderate expression (P = 0.198)." (PMID 22919486, 2012). "Using CD68 (a specific marker of monocytes/macrophages), it was demonstrated that the cells at the IF most strongly staining for cathepsin D were of monocytes/macrophage phenotype rather than being cancer cells." (PMID 22919486, 2012). "The overexpressed proteins, including actinin α1 isoform (ACTN1), annexin A5 (ANXA5), cathepsin D (CTSD), F-actin-capping protein subunit β (CAPZB), inorganic pyrophosphatase (PPA1), and tubulin α1c chain (TUBA1C), are related to cellular structure, growth, or cancer cell invasion." (PMID 38249992, 2024). "Using the Pan-Cancer TCGA dataset gathering RNA-seq data from 11,060 patients, an anticorrelation between TET2 expression and mRNA levels of lysosome proteins was confirmed for CLN3, CTSD, CTSF, CTSZ, IFI30, and NAGLU, suggesting TET2 might down-regulate lysosomal genes in various types of cancer." (PMID 35351824, 2022).